CCR4 (C-C motif chemokine receptor 4)
Diseases named in the same sentence as CCR4 in open-access papers (continued):
Sharing a sentence is not in itself a finding about the gene and the disease.
uveitis (4 papers, 2008 to 2023). An inflammatory process affecting a part of or the entire uvea. "Upregulated CCR4 expression was previously observed in keratoconjunctivitis, glaucoma, and uveitis, in addition to its downregulation in dry eyes." (PMID 36658547, 2023). "CCR4 was overexpressed in the epithelial conjunctival cells of uveitis, and its overexpression suggested involvement of the Th2 system on the ocular surface while participation of Th1 is usually considered to be favored in intraocular pathogenesis, at least in experimental autoimmune uveitis." (PMID 19104678, 2008). "Recently, our group has investigated the Th1 and Th2 inflammatory cascades by assessing CC chemokine receptor 4 (CCR4) and CCR5 expression in conjunctival cells in uveitis." (PMID 19104678, 2008). "Notably, our previous induced uveitis rodent studies demonstrated SOCS1-KIR mediated decreases in the chemokines CCL2, CCL20 and CXCL9, in addition to the chemokine receptors CCR2, CCR4, CCR6 and CXCR35,25." (PMID 35505065, 2022).
airway hyperresponsiveness (3 papers, 2008 to 2023). "The utility of developing CCR4 antagonists is controversial because CCR4-deficient mice do not show any change in cell recruitment in the lung or induction of airway hyperresponsiveness." (PMID 18315837, 2008). "Moreover, antibody-mediated neutralization of CCR4 or CCR4 deletion blocks iNKT cell migration to the lungs, thereby attenuating the airway hyperresponsiveness (AHR) induced in mice by pulmonary administration of antigen or αGalCer47–49." (PMID 37696892, 2023).
Cirrhosis (3 papers, 2016 to 2023). A chronic disorder of the liver in which liver tissue becomes scarred and is partially replaced by regenerative nodules and fibrotic tissue resulting in loss of liver function. "In contrast to CCR2 and CCR4, CD62L, a selectin implicated in preferential recruitment of blood monocytes to sites of inflammation, was specifically increased on monocytes from patients with decompensated cirrhosis." (PMID 27309850, 2016).
dilated cardiomyopathy (3 papers, 2020 to 2021). Cardiomyopathy which is characterized by dilation and contractile dysfunction of the left and right ventricles. "Silencing of the components of the CCR4-Not complex in Drosophila results in myofibrillar disarray and dilated cardiomyopathy." (PMID 34208845, 2021). "A greater susceptibility to heart failure has also been observed in mutants of the chromatin remodelling via Carbon Catabolite Repression 4 (CCR4)–Negative on TATA-less (Not) (CCR4–Not) complex (Not3), leading to cardiac contractility defects in mice and dilated cardiomyopathy in flies." (PMID 34831301, 2021). "Furthermore, the cardiac-specific knockdown of Drosophila orthologs of CCR4-NOT genes in vivo (CNOT1/Not1 and CNOT7/8/Pop2) was either lethal or resulted in dilated cardiomyopathy, reduced contractility or a propensity for arrhythmia." (PMID 32471864, 2020).
experimental autoimmune encephalomyelitis (3 papers, 2020 to 2023). An autoimmune demyelinating disease of the central nervous system that is produced experimentally in animals by the injection of homogenized brain or spinal cord in Freund's adjuvant. "The evidence is consistent for the involvement of CCL17, CCL22 and CCR4 in the experimental autoimmune encephalomyelitis model of MS72–74." (PMID 32179746, 2020). "The importance of CCR4 and its two ligands, TARC (CCL17) and CCL22, has also been noticed in central nervous system autoimmunity and studied in the experimental autoimmune encephalomyelitis murine model." (PMID 34539561, 2021).
fungal infection (3 papers, 2015 to 2024). "This suggests that CCR4 absence could provide protective effects against allergic pulmonary reactions and fungal infection in mice." (PMID 39194909, 2024). "Our data showing CCR4 as important for the recruitment of Tregs to the target tissue corroborate those obtained by previous works that correlated the expression of CCR4 to Treg migration to the lung and skin in experimental models of airway allergic inflammation and fungal infection, respectively." (PMID 31611578, 2019). "Consequently, the CCR4-/- septic mice were not susceptible to secondary fungal infection, in contrast with the WT septic mice." (PMID 26197455, 2015).
head and neck cancer (3 papers, 2021 to 2024). A primary or metastatic malignant neoplasm affecting the head and neck. "Meanwhile, other studies indicated that head and neck cancer patients with high CCR4 expression had a better prognosis." (PMID 38256152, 2024). "Targeting of CCR4 decreased cancer cell migration and metastasis in head and neck cancer." (PMID 37371612, 2023).
heart failure (3 papers, 2011 to 2021). Inability of the heart to pump blood at an adequate rate to meet tissue metabolic requirements. "We recently demonstratedthat knockdown of CCR4-Not components in Drosophila and in miceresulted in cardiomyopathy and heart failure and that a common NOT3SNP (rs36643) in humans correlates with altered cardiac QT intervals, a frequentcause of sudden cardiac death." (PMID 21541028, 2011).
intracerebral hemorrhage (3 papers, 2022 to 2025). A cerebrovascular disorder characterized by bleeding into one or both cerebral hemispheres including the basal ganglia and the cerebral cortex. "Our previous studies demonstrated that CCL17 and its receptor CCR4 play crucial roles in neuroinflammation and microglial activation following intracerebral hemorrhage (ICH)." (PMID 39996481, 2025).
ischemic stroke (3 papers, 2022 to 2024). A stroke disorder caused by obstruction of blood flow to the brain, due to thrombotic (local blood clot formation) or embolic (due to a blood clot or other material traveling from another site) event. "Our results suggest a novel idea of overexpressing CCR4 to enhance the therapeutic effects of Treg cells in response to microglia-derived chemokines in the acute phase of the ischemic stroke animal model." (PMID 38702399, 2024). "Relating to previous studies regarding CCL22-CCR4 interactions in Treg cell trafficking and their ameliorating effects, the therapeutic potential of CCR4-overexpressing Treg cells can be further studied during the acute and recovery phases of ischemic stroke." (PMID 38702399, 2024). "M1 macrophage and microglial polarization in ischemic stroke are partially dependent on CCR4 via the chemokine‐like factor 1 (CKLF1)‐mediated NF‐κB pathway." (PMID 37452512, 2023). "Its expression increases during the early phase of ischemic stroke and its main receptor in ischemic stroke is CCR4." (PMID 37452512, 2023). "Using CCR4/5 antagonists, it was found that only the CCR4 antagonist had the same effect as CKLF1, suggesting that CCR4 is the main receptor in ischemic stroke." (PMID 37452512, 2023).
liver disease (3 papers, 2011 to 2023). "TGF-β1, a critical molecule that participates in fibrosis progression and in HCC development, dropped significantly post CCR4 blockade, suggesting CCR4 as a critical target to control Tregs mediated immune suppression and progression of liver disease." (PMID 37081509, 2023). "The exact function of Treg in hepatic disease and their migration into the liver is still a matter of debate; however, CCR4 and CXCR3 appear to be involved in Treg recruitment and positioning within the liver." (PMID 21197451, 2011). "Human liver-infiltrating Th17 expressed high levels of chemokine receptors, CCR6 68 ± 11% (mean ± SD), CXCR3 47 ± 11%, and CCR4 44 ± 13%, irrespective of the cause of liver disease." (PMID 22796894, 2012). "Understanding the chemokines and chemokine receptors promoting hepatic Th17 cell recruitment (possibly CCR6 or CCR4) might reveal new therapeutic targets interfering with Th17 migration or differentiation in liver disease." (PMID 21197451, 2011).
lung diseases (3 papers, 2009 to 2024). "The CCL17-CCR4 axis is implicated in IPF progression, suggesting potential benefits from targeting CCL17 or CCR4 in fibroproliferative lung diseases." (PMID 39768150, 2024). "CCL17 promotes the recruitment, activation, and development of Th2-polarized cells expressing CCR4 and plays an essential role in the development of lung diseases." (PMID 35743888, 2022). "To further elucidate the roles of these chemokines in recruiting cells to the lungs in fibrotic lung diseases, we analyzed CCR4-positive BAL fluid cell subpopulations by flow cytometry." (PMID 19715610, 2009).
myocardial infarction (3 papers, 2016 to 2025). Gross necrosis of the myocardium, as a result of interruption of the blood supply to the area, as in coronary thrombosis. "Our suggestion that CCR4 and CXCR3 might participate in neuroinflammation is based on previous reports associating CCR4 with recruitment of white blood cells and production of cytokines after myocardial infarction and correlated CXCR3 with leukocyte accumulation in focal stroke and gliosis." (PMID 27635404, 2016). "An interesting study found that CCL17 and CCL22 can participate in the regulation of Treg chemotaxis as competitive biased ligands of CCR4 in myocardial infarction." (PMID 41266856, 2025). "CCL22 is involved in CCR4-mediated cardiac cell migration and CCL22/CCR4 polymorphisms have been associated to patients diagnosed with myocardial infarction." (PMID 35784739, 2022).
ovarian tumors (3 papers, 2012 to 2022). "Primary tumor cells and tumor-associated macrophages (TAMs) from ovarian tumors produced CCL22, a ligand for CCR4, which was crucial for the migration Tregs, whose CCR4 expression was higher than other CD4+ T cells." (PMID 33603130, 2022). "We further looked at the subset of Tregs within this population with potential capacity migrate into an ovarian tumor microenvironment, as determined by the extracellular expression of the CCL22 chemokine receptor, CCR4." (PMID 24213326, 2012).
periodontitis (3 papers, 2017 to 2024). An acute or chronic inflammatory process that affects the tissues that surround and support the teeth. "In periodontitis, chronic periodontitis patients showed high levels of CCL22 and CCR4 compared with healthy donors." (PMID 34177907, 2021).
pneumonitis (3 papers, 2009 to 2023). An inflammatory process affecting the lung parenchyma. "CCR4-expressing CD103+ Tregs are important for lung-specific recruitment of Tregs, as CCR4-deficient Tregs have limited lung trafficking capabilities, resulting in pneumonitis." (PMID 37463441, 2023).
Thrombocytopenia (3 papers, 2008 to 2020). A reduction in the number of circulating thrombocytes. "Indeed, there was decreased hemoconcentration, thrombocytopenia, liver damage, systemic inflammation and leukocyte activation in CCR4–/– mice." (PMID 21206747, 2010).
allergic aspergillosis (2 papers, 2021 to 2024). "Further, the CCR4 antagonist prevented allergic bronchopulmonary aspergillosis in susceptible mice, and in a murine model of cystic fibrosis, a genetic disorder characterized by chronic pulmonary inflammation and recurrent infections." (PMID 33669094, 2021). "A recent study has further indicated that a CCR4-antagonist molecule known as SP50 is effective not only in preventing allergic aspergillosis but also in escaping invasive aspergillosis when inoculated with A. fumigatus lethal doses." (PMID 39194909, 2024).
aspergillosis (2 papers, 2021 to 2024). Aspergillosis is an infection, growth, or allergic response caused by the Aspergillus fungus. "Clinicians should be aware of possible atypical presentations of aspergillosis during treatment with CCR-4 antagonists." (PMID 39194909, 2024). "Taken together, these observations raise the chance that the CCR-4 may be involved in the control of aspergillus infection and that atypical clinical presentation of aspergillosis may occur if the CCR-4 pathway is altered." (PMID 39194909, 2024). "In conclusion, the present manuscript demonstrates that CCR4 antagonists may be successfully used to prevent or treat aspergillosis in a variety of clinical settings and emphasizes the need for alternative drug development strategies for clinical translation." (PMID 33669094, 2021). "Our results indicate that CCR4 antagonists can protect from aspergillosis and allergic bronchopulmonary aspergillosis (ABPA) in susceptible mice and in a murine model of cystic fibrosis, thus extending the clinical indications for therapeutic development of CCR4 targeting drugs." (PMID 33669094, 2021). "We then analyzed the effects of the CCR4 antagonist in other models of aspergillosis." (PMID 33669094, 2021). "Therefore, by resorting to the CpG/Ag model, we asked whether the vaccination potential of Cat1p against pulmonary aspergillosis could be improved by the CCR4 antagonist." (PMID 33669094, 2021).
atopic asthma (2 papers, 2004 to 2018). An asthma that is characterized by symptoms that are triggered by an allergic reaction caused by inhaled allergens such as dust mite allergen, pet dander, pollen and mold. "In line with this, the difference in the frequency of CCR4+ CD4+ T cells between atopic asthma patients and control subjects was even greater when we compared them in Tcm cells." (PMID 29507584, 2018). "We thus concluded that adult atopic asthma patients have increased CCR4+ CD4+ T cells in their blood and this increase is mainly due to the increase of CCR4+CD45RA−CD45RO+CCR7+ CD4+ T cells." (PMID 29507584, 2018). "It was also important to note that current therapy (i.e. corticosteroids, β-agonists, leukotriene inhibitors, and combinations thereof) was not capable of reducing the frequency of either total CD4+ Tcm or CCR4+ CD4+ Tcm cells in atopic asthma patients." (PMID 29507584, 2018). "Our findings raise a fundamental question concerning the mechanisms responsible for the increased numbers of CCR4+ CD4+ Tem cells in atopic asthma patients." (PMID 29507584, 2018). "This study reports for the first time that an increase of long-lived CD4+ Tcm cells along with CCR4+ CD4+ Tcm cells is one of the major features of circulating blood T cells in adult atopic asthma patients." (PMID 29507584, 2018). "In line with the increase of CCR4+ T cells in patients, T cells from atopic asthma patients secreted more of IL-5 and IL-13 than T cells from non-asthmatic control subjects." (PMID 29507584, 2018). "In our study, we found that atopic asthma patients have more circulating CCR4+ CD4+ T cells and this was mainly due to the increase of CD4+ Tcm cells." (PMID 29507584, 2018). "This increase of CCR4+ CD4+ Tcm cells can be seen across atopic asthma subtypes and severities." (PMID 29507584, 2018). "As such, we analyzed the frequency of CD4+ T cell subsets expressing CCR4 in atopic asthma patients and non-asthmatic control subjects." (PMID 29507584, 2018). "CCR4+CCR7+ memory, but not CCR4+CCR7− memory, α4+, and CTLA4+ CD4+ T cells in patients show significant clinical implications in atopic asthma." (PMID 29507584, 2018). "Taken together, we concluded that the frequency of CCR4+ CD4+ T cells, particularly CCR4+CD45RA−CD45RO+CCR7+ CD4+ T cells, varies among atopic asthma subtypes, but are not significantly influenced by corticosteroid or leukotriene inhibitor treatments." (PMID 29507584, 2018).
brain injuries (2 papers, 2014 to 2021). "CCR4 expression also increased in patients with traumatic brain injuries, and it has been associated with increased immunosuppressive cytokine expression via activated T-lymphocytes." (PMID 33648537, 2021). "CCR4, as a functional receptor for CKLF1, is prevalently expressed on T cells and plays an essential role in the recruitment of T cells into the ischemic region in the later stages of ischemic brain injury." (PMID 24946684, 2014).
brain tumor (2 papers, 2017 to 2021). "The CCL2–CCR4 axis is required for Treg cell recruitment, and CCR4− deficient Treg cells show defective recruitment in brain tumors." (PMID 29312296, 2017).
cardiac hypertrophy (2 papers, 2022 to 2024). "This mechanistic study revealed that CCL17 recruits Th2 cells through binding to CCR4, thus perturbing T cell subset balance, promoting fibrotic-factor release (predominantly IL-4 and IL-17), and resulting in cardiac hypertrophy, fibrosis, and subsequent HF." (PMID 35687056, 2022).
cardiomyopathies (2 papers, 2011 to 2020). "Of note, the role of the causative mutation in the overlap between channelopathies and cardiomyopathies is not fully understood, and the role of possible new players acting as phenotype modifiers, like the CCR4-NOT complex, has yet to be determined." (PMID 32471864, 2020).
Cerebral ischemia (2 papers, 2019 to 2024). Restriction of arterial blood supply to the brain associated with insufficient oxygenation to support the metabolic requirements of the tissue. "Compound IMM-H004 is a novel coumarin derivative screened from a CKLF1/C-C chemokine receptor type 4 (CCR4) system and has been reported to improve cerebral ischemia/reperfusion injury." (PMID 30987181, 2019). "When specifically inhibiting the CKLF1/CCR4 axis, the activation of NLRP3 and the subsequent inflammatory response process could be further inhibited, thus protecting neurological function and improving cerebral ischemia." (PMID 38773776, 2024).
cervical cancer (2 papers, 2017 to 2024). A primary or metastatic malignant neoplasm involving the cervix. "Cervical cancer (CC) is an important public health problem for women, gene expression patterns which were governed by epigenetic modifications can result in CC, CC-chemokine receptor 4 (CCR4) interacts with C-C-motif ligand 22 (CCL22) is associated with tumor progression or metastasis." (PMID 39513112, 2024). "The FoxP3, CCL22 and CCR4 mRNA level in local immune microenvironment of normal cervix was lower than that in cervical cancer." (PMID 28086903, 2017). "The correlation analysis indicated that in immune microenvironment of cervical cancer, the mRNA level of CCL22 and CCR4 was strengthened as the Foxp3 mRNA level increased and vice verse." (PMID 28086903, 2017). "In summary, these results showed that the level pattern of mRNA of FoxP3, CCL22/CCR4, OX40L/OX40 and Smad3 in cervical cancer immune microenvironment distinctly differed from that in normal cervix." (PMID 28086903, 2017).
colon adenocarcinoma (2 papers, 2012 to 2015). "A study of 31 patients with colon adenocarcinoma revealed that CCR4+ CTLA4hi Treg cells accumulated in the tumors." (PMID 25352158, 2015). "In conclusion, this study show accumulation of CCR4+CTLA-4hi Treg stably expressing FOXP3 in colon adenocarcinomas, and close contact between Treg and conventional CD4+ and CD8+ T cells." (PMID 22319577, 2012).
dengue (2 papers, 2010 to 2012). "In the present work we have investigated the putative role of CC chemokine receptors CCR1, CCR2 and CCR4 in the context of experimental Dengue virus infection." (PMID 21206747, 2010). "It is difficult to suggest the mechanism by which CCR4 may contribute to the pathogenesis of dengue." (PMID 21206747, 2010).
dry eye (2 papers, 2022 to 2023). "Firstly, the extracellular ligand IL-6 directs T cell recruitment by regulating local chemokine secretion and chemokine receptor (CCR4, CCR5, CXCR3, etc.)expression on the CD3+ infiltrate, thus leading to the occurrence of dry eye." (PMID 36522768, 2022).
dyslipidemia (2 papers, 2016 to 2024). "Although different associations with cardiometabolic risk factors indicate disease-specific changes, overlapping pattern was found for the associations between CCR4+ T lymphocytes and vascular inflammation, CXCR4+ subsets and albuminuria as well as CXCR3+ T lymphocytes and dyslipidemia." (PMID 39109081, 2024). "Our data suggest that PT has the potential to regulate insulin resistance and metabolic syndrome by lowering the mRNA expression of PDPK-1, CCR4, CCR6, and CCL4L2 in PBMCs." (PMID 27869712, 2016).